ASS1 (argininosuccinate synthase 1)
Diseases named in the same sentence as ASS1 in open-access papers (continued):
Sharing a sentence is not in itself a finding about the gene and the disease.
mesothelioma (continued). "Although differences can be due to different antibodies or technique, both of our studies suggest that a significant number of patients with mesothelioma will have elevated ASS1 expression." (PMID 26982031, 2016). "Using this screening approach, in which genes upregulated in 3D were cross-referenced against published mesothelioma genes, we found that ASS1 is upregulated in 3D and also in mesothelioma." (PMID 26982031, 2016). "Reduction of ASS1 expression by siRNA significantly sensitized mesothelioma spheroids to the pro-apoptotic effects of bortezomib and of cisplatin plus pemetrexed." (PMID 26982031, 2016). "For the paired samples, ASS1 expression in mesothelioma was significantly greater than in the normal tissues." (PMID 26982031, 2016). "In addition, in the first report of ASS1 protein expression in mesothelioma, 63% of mesotheliomas were found to have low expression (0–1+) while 37% had high expression (2–3+)." (PMID 26982031, 2016). "We also have uncovered a survival role for ASS1, which may be amenable to targeting to undermine mesothelioma multicellular resistance." (PMID 26982031, 2016). "Hence, to confirm our findings, we analyzed ASS1 expression at the protein level in both mesothelioma spheroids and patient samples." (PMID 26982031, 2016). "Thus, ASS1 appears to be a gene relevant to mesothelioma biology, with a significance as yet unknown." (PMID 26982031, 2016). "Nonetheless, our data shows that ASS1 is a mesothelioma gene, as also described by Melaiu and colleagues, is upregulated when mesothelioma cells, but not normal mesothelial cells, are grown as 3D spheroids, and that reduction of ASS1 protein levels has potential therapeutic value." (PMID 26982031, 2016). "In mesothelioma cells exhibiting ADI-PEG20 resistance, it is believed that this resistance is induced by regain of ASS1 expression by demethylation of the ASS1 promoter." (PMID 35910381, 2022). "The enzyme argininosuccinate synthetase 1 (ASS1) leads to arginine biosynthesis from citrulline and is epigenetically suppressed in a high proportion of mesothelioma cell lines." (PMID 32226777, 2020). "Taken together, our data indicate that a combination treatment of GC7 and ADI-PEG20 has significant potential clinical utility to minimize drug resistance in patients with ASS1-ve mesothelioma tumors, for which therapeutic options currently do not exist." (PMID 39758821, 2025). "Approximately 50% of mesotheliomas do not express argininosuccinate synthetase 1 (ASS1), the rate-limiting enzyme in arginine biosynthesis, making arginine depletion with pegylated arginine deiminase (ADI-PEG20) an attractive therapeutic strategy." (PMID 39758821, 2025). "In support of this, our bioinformatic analysis of ADI-PEG20 treated ASS1-negative mesothelioma cells demonstrated significant up-regulation of XBP1 in concert with the pro-inflammatory cytokine response." (PMID 37010783, 2023). "Arginine is an essential amino acid for cell survival and in mesothelioma, its metabolism is often disrupted due to the decreased or absent levels of arginine succinate synthetase 1 (ASS1), particularly in the sarcomatoid and biphasic subtypes." (PMID 37298116, 2023). "Currently, the down-regulation of ASS1 expression is extensively studied in mesothelioma, non-small-cell lung cancer, myxofibrosarcomas and others." (PMID 35910381, 2022). "Epigenetic ASS1 gene silencing via DNA methylation has been reported in mesothelioma and other cancers and is not inducible." (PMID 26771234, 2016). "A recently completed phase II trial of single-agent ADI-PEG 20 in ASS1-negative patients with mesothelioma also revealed encouraging efficacy results." (PMID 25164070, 2014). "About 60% of non-epithelioid mesothelioma cases and 20% of mesothelioma cases with epithelioid histology are arginine-auxotrophic due to the lack or decreased expression of arginine succinate synthetase 1 (ASS1), which catalyzes the rate-limiting step in the biosynthesis of this amino acid." (PMID 40918456, 2025).
mesothelioma (continued). "Indeed, arginine deprivation is synthetically lethal in cancers, such as mesothelioma, that are argininosuccinate synthetase 1 (ASS1)-negative." (PMID 32318342, 2020). "In the first set of 88 mesotheliomas, only 8 mesotheliomas completely lacked ASS1 expression." (PMID 26982031, 2016). "Since macrophages rescued ASS1-negative MPM cells from ADI-PEG20-induced cytotoxicity via argininosuccinate, we employed clodronate-containing liposomes (CLIP) which deplete macrophages in mesothelioma mouse models, in combination with arginine deprivation in vivo." (PMID 37010783, 2023).
prostate carcinoma (24 papers, 2012 to 2025). A carcinoma that arises from epithelial cells of the prostate gland. "In argininosuccinate synthetase 1 (ASS1)-deficient prostate cancer cells, arginine depletion induces giant autophagosome formation, nuclear membrane rupture, and interestingly cytoplasmic histone-associated DNA encaptured by autophagosomes." (PMID 35047516, 2021). "In cancers such as lymphomas, bladder cancer, and prostate cancer, diminished ASS1 expression can be due to methylation of the ASS1 promoter." (PMID 36276057, 2022). "ADI-PEG20 induced autophagic and apoptotic cell death in ASS1-low prostate cancer cell lines including CWR22Rv1 and PC3." (PMID 34158865, 2021). "We have characterized two additional ASS1-low castration-resistant prostate cancer cell lines, CWR22Rv1 and DU145 and isolated their ADI-resistant derivatives." (PMID 33664852, 2021). "In this study, we wished to explore the molecular basis of the coordinated regulation of the metabolic genes in ASS1-low prostate cancer cells." (PMID 33893278, 2021). "To generalize our observations to prostate cancer cells, we developed ADI-resistant clones (PC3-ADIR) and ASS1-overexpressing clones (PC3-ASS1) in prostate cancer PC3 cell line." (PMID 33664852, 2021). "TREM1/CCL2 activation, in addition to restored ASS1 expression, as a key pathway involved in full ADI-resistance in breast and prostate cancer models." (PMID 34884583, 2021). "Previously, we have used ASS1-low breast (e.g., MDA-MB-231) 23, 24 and prostate cancer (e.g., CWR22Rv1 and PC3) 25, 26 as models to study arginine-starvation therapy." (PMID 33664852, 2021).
bladder cancer (18 papers, 2017 to 2025). "Decitabine reestablished cisplatin susceptibility in resistant bladder carcinoma cells by increasing ASS1 expression." (PMID 40956032, 2025). "ASS-1 deficient bladder cancer cells are ADI-PEG-20 sensitive, activating the GCN2-eIF2α-ATF4 pathway and inducing C/EBP homologous protein (CHOP) expression." (PMID 39516654, 2023). "Loss of ASS1 has been found in many cancers that are addicted to extracellular arginine for survival, including a large proportion of bladder cancers." (PMID 35326708, 2022). "Loss of ASS1 expression has been associated with poor prognosis in bladder cancer and glioblastoma and recent data indicate that ASS1 downregulation supports cancer growth allowing aspartate channeling into pyrimidine biosynthesis." (PMID 30108309, 2018). "Furthermore, ADI-PEG 20 selectively arrested tumor growth in mice with ASS1-deficient bladder cancer cells." (PMID 37445845, 2023). "This resulted in the selective apoptosis in the ASS-1-deficient bladder cancer cells." (PMID 39516654, 2023). "One opportunity may be related to loss of argininosuccinate synthetase (ASS1), a rate-limiting enzyme in the synthesis of arginine, in bladder cancer." (PMID 35326708, 2022). "Recent studies showed that ASS1 may have tumor suppressor function and that ASS1 deficiency is associated with clinical aggressiveness in nasopharyngeal carcinoma, myxofibrosarcomas and bladder cancer." (PMID 28187218, 2017). "Two studies have indicated that ASS1 reduced colony forming, proliferation, and invasion of sarcoma and bladder cancer cells and functions as a tumor suppressor gene (." (PMID 35694253, 2022). "Argininosuccinate synthase 1 (ASS1) in cisplatin-resistant bladder cancer cells is hypermethylated, resulting in greatly downregulated expression, suppressing the apoptotic effects of cisplatin." (PMID 35004688, 2021). "ASS1 is significantly downregulated in cisplatin‐resistant bladder carcinoma cells." (PMID 40956032, 2025). "In addition, the cisplatin resistance in bladder cancer was reported related to argininosuccinate synthase 1 and spermidine/spermine N1-acetyltransferase-mediated amino acid metabolism." (PMID 37252635, 2023). "In bladder cancer, ADI-PEG 20 was synthetically lethal in ASS1-methylated bladder cells in vitro, and a decrease in intracellular thymidine levels was observed." (PMID 37445845, 2023). "A recent study has shown that argininosuccinate synthase 1 (ASS1) and spermidine/spermine N1-acetyltransferase (SAT1), the central enzymes for arginine metabolism, are hypermethylated in cisplatin-resistant bladder cancer cells." (PMID 33511116, 2020).
pancreatic cancer (18 papers, 2016 to 2024). "Arginine-deprivation therapies, such as ADI-PEG 20—a pegylated form of arginine deiminase—specifically target pancreatic cancer cells deficient in ASS1." (PMID 38756774, 2024). "The deficiency in OTC and ASS1 in human pancreatic cancer facilitates this combination approach, which also serves as a predictive biomarker for the response to this novel therapeutic strategy." (PMID 39570001, 2024). "Our findings also indicated that OTC deficiency is more prevalent than ASS1 in human pancreatic cancer." (PMID 39570001, 2024). "Our findings suggest heightened susceptibility of pancreatic tumors deficient in arginine biosynthesis enzymes ASS1 and OTC." (PMID 39570001, 2024). "The treatment was found to be active in previously treated and untreated patients with advanced pancreatic cancer, including those with ASS1-deficient and -proficient tumors." (PMID 37445845, 2023). "Based on the findings, clinical trials assessing combination of radiation therapy and ADI-PEG20 in ASS1-deficient pancreatic cancer patients deserve to be considered." (PMID 33117704, 2020). "It has been reported that pancreatic tumors and pancreatic cancer cell lines are frequently deficient in ASS1." (PMID 32353864, 2020). "More importantly, anti-cancer activity was observed in previously treated and untreated patients with advanced pancreatic cancer and in patients with ASS1-deficient and -proficient tumors." (PMID 32353864, 2020). "In an advanced pancreatic cancer phase 1/1B single-arm clinical trial, a regimen combining ADI-PEG20, gemcitabine, and nab-paclitaxel demonstrated tolerability and efficacy in both previously treated and untreated advanced pancreatic cancer patients, including those with ASS1-deficient tumors." (PMID 38756774, 2024). "ASS1-low tumors in pancreatic cancer patients have been associated with a poor prognosis, suggesting that arginine deprivation therapy might play a role in treating pancreatic cancer." (PMID 37445845, 2023). "In addition, ADI-PEG 20 was found to potentiate the radio-sensitivity of ASS1-deficient pancreatic cancer cells, leading to apoptosis." (PMID 37445845, 2023). "Moreover, ADI-PEG20 enhanced radiation-mediated apoptosis by triggering the ER stress pathway and sensitized ASS1-deficient pancreatic cancer to radiation both in vitro and in vivo." (PMID 33117704, 2020). "Indeed, in a clinical study combining ADI-PEG20 with nab-paclitaxel and gemcitabine in pancreatic cancer, objective results were observed in both ASS1-proficient and -deficient patients." (PMID 30108309, 2018). "From our in-house cohort and online database analysis, we found that the majority of the patients with pancreatic cancer exhibited deficiencies in both ASS1 and OTC enzymes, suggesting that the combination of arginine deprivation and canavanine could be particularly effective in these patients." (PMID 39570001, 2024). "Reduction in ASS1 expression has been postulated as an independent prognostic biomarker in pancreatic cancer and sarcomas." (PMID 35655758, 2022). "They found that increasing sd/miR-1291 reduced ASS1 levels in the ASS1-abundant L3.3 pancreatic cancer cell line and sensitized them to arginine deprivation in vitro." (PMID 36009366, 2022). "ASS1 expression can be evaluated on surgical biopsy specimens or cell blocks for fine needle aspiration of pancreatic tumor." (PMID 28187218, 2017). "In pancreatic cancer, reduced ASS1 expression predicts unfavorable tumor behaviors such as lymph node metastasis, local invasion and resistance to gemcitabine-based chemotherapy." (PMID 27683125, 2016). "It is noteworthy that the effectiveness of this cotreatment in both ASS1− and ASS1+ pancreatic cancer cells is unique to the arginine depletion imposed by PEG-BCT-100 but may not apply to other arginine-depleting agents." (PMID 39570001, 2024).
pancreatic cancer (continued). "Consequently, treatments that deplete arginine levels can markedly impair the proliferation, invasion, and migration of pancreatic cancer cells, characterized by reduced ASS1 activity." (PMID 38756774, 2024). "We found that arginine depletion hindered the migration of pancreatic cancer cells with low ASS1 expression, and that the migration of these cells could be restored by GAA supplementation." (PMID 37370109, 2023). "Furthermore, pano-binostat, a non-selective histone deacetylase inhibitor, and ADI-PEG 20 were effective in suppressing ASS1-low pancreatic cancer growth in mouse xenograft models." (PMID 37445845, 2023). "Consistent with this notion, previous study has shown that five of seven pancreatic cancer cell lines lacked ASS1 expression and that arginine deprivation by treatment with PEG-ADI specifically inhibited the growth of pancreatic cancer cell lines that lack ASS1 expression both in vitro and in vivo." (PMID 28187218, 2017). "SREBF1 (Sterol Regulatory Element Binding Transcription Factor), ASS1 (Argininosuccinate Synthase) and HSPA-5 (Homo Sapiens Heat Shock protein 5) were selected for further validation by RT-qPCR due to their known association with tumor processes and with pancreatic cancer development." (PMID 30913248, 2019). "In line with our own cohort, pancreatic cancers showed minimal expression of both OTC and ASS1 compared with other cancer types." (PMID 39570001, 2024). "Additionally, we evaluated the expression levels of ASS1 and OTC in pancreatic cancer and their correlation with the efficacy of the combination treatment." (PMID 39570001, 2024). "IHC staining was performed on 61 pancreatic cancer specimens, revealing that a majority of patients exhibited low or no expression of ASS1 and OTC enzymes." (PMID 39570001, 2024). "As low ASS1 and OTC expressions were shown to facilitate the response to the combination treatment, we then investigated the clinical relevance of this therapeutic approach by analyzing our in-house patient cohort with pancreatic cancer." (PMID 39570001, 2024). "Our findings also suggested that pancreatic tumors lacking the key enzymes in arginine biosynthesis, argininosuccinate synthetase 1 (ASS1) and ornithine transcarbamylase (OTC), were more susceptible to the treatment." (PMID 39570001, 2024). "ADI-PEG 20 has shown promise in pancreatic cancer treatment, particularly by inhibiting the growth of xenografts lacking ASS1 expression and inducing cell apoptosis in pancreatic cancer cell lines." (PMID 37445845, 2023). "However, metastatic pancreatic cancer cells with high ASS1 and GATM expression maintained higher levels of intracellular arginine and GAA than those with low ASS1 and GATM expression." (PMID 37370109, 2023). "Arginine depletion was reported to inhibit the migration of pancreatic cancer cells that lacked ASS1 expression and were dependent on exogenous arginine." (PMID 37370109, 2023). "They found that ADI-PEG 20 potently radiosensitized ASS1-deficient pancreatic cancer cells (MiaPaCa-2, Panc-1, AsPc-1, HPAC, and CaPan-1), but not ASS1-expressing cell lines (Bxpc3, L3.6pl, and SW1990)." (PMID 32353864, 2020). "Notably, 57.3% of the patients lacked both OTC and ASS1 enzymes, indicating most of the pancreatic cancers are arginine-auxotrophic." (PMID 39570001, 2024). "Additionally, arginine depletion significantly inhibited the proliferation of pancreatic cancer cells regardless of the ASS1 expression level." (PMID 37370109, 2023).